ALDH1L1 (aldehyde dehydrogenase 1 family member L1)
Diseases named in the same sentence as ALDH1L1 in open-access papers (continued):
Sharing a sentence is not in itself a finding about the gene and the disease.
tumor (continued). "In serial sections, tumor-adjacent reactive areas contain approximately an equal fraction of astrocytes (ALDH1L1+) and microglia (Iba1+) at 18–19% each, though high variability exists between patient samples." (PMID 35906273, 2022). "We investigated this putative function of the protein by comparing malignant tumor growth in wild-type and Aldh1l1 knockout mice using the DEN model of liver carcinogenesis." (PMID 34203215, 2021). "Metabolomic analysis offers further support for the idea that ALDH1L1 contributes more control at a later stage of tumor progression." (PMID 34203215, 2021). "Larger tumor nodules (macroscopic tumors with at least one linear dimension >0.5 cm) were observed starting at 20 weeks in Aldh1l1 KO and 28 weeks in WT mice." (PMID 34203215, 2021). "The role of ALDH1L1 as the regulator of tumor proliferation is in agreement with previous findings that the expression of this enzyme oscillates during the cell cycle, being the lowest in the S-phase of actively proliferating cells." (PMID 34203215, 2021). "To understand the metabolic basis for the promotion of tumor proliferation in Aldh1l1 KO mice, we performed a metabolomic analysis of liver samples at 10 and 20 weeks post-DEN injection." (PMID 34203215, 2021). "By contrast, the inhibition of oxidative phosphorylation inhibition using phenformin in Aldh1l1−/−; KrasLA2 mice dramatically decreased the number of tumor nodules and tumor area by up to 50%." (PMID 32481524, 2020). "Tumor area was also reduced about 54% in KrasLA2; Aldh1l1−/− mice with phenformin treatment while that was decreased about 14% in KrasLA2; Aldh1l1−/− mice." (PMID 32481524, 2020). "ALDH1L1 expression was highly increased in tumor nodules of the lung tissue from the KrasLA2 murine mouse model." (PMID 32481524, 2020). "Statistical significance of the difference in ALDH1L1 level between tumor and normal tissues for 16 paired samples was assessed by the Mann–Whitney test: p < 0.02." (PMID 29868117, 2018). "On one hand, hypermethylation and silencing of the gene even at early stages can indicate that silencing of ALDH1L1 is prerequisite for malignant transformation and the gene can be considered a tumor suppressor." (PMID 29868117, 2018). "It was suggested that ALDH1L1 limits proliferation capacity of the cell and thus functions as putative tumor suppressor." (PMID 29979702, 2018). "We performed multicolor immunohistochemical staining on human HNSCC tissues and mouse tongue orthotopic tumor model tissues, and found colocalization of Aldh1l1 and S100 (a marker primarily expressed in Schwann cells), indicating that Aldh1l1 is expressed in glial cells of the tongue." (PMID 41330921, 2025). "Thus, as an adaptive response, most cancer cells show a downregulation or loss of ALDH1L1, which results in an increased pool of 10-formyl-THF, supporting enhanced nucleotide biosynthesis and tumor progression." (PMID 39273288, 2024). "ALDH1L1 may inhibit tumor growth by reducing the availability of 10-formyl-THF, a critical component for purine synthesis, thereby limiting DNA synthesis and cell proliferation." (PMID 39273288, 2024). "We used stable ALDH1L1‐overexpressing and ‐knockdown cell lines to investigate the key regulatory proteins of these classic pathways, it was found that the tumor suppressor effect of ALDH1L1 in OSCC may be through other pathways." (PMID 36336972, 2023). "Thus, our ALDH1L1-expressing HuH-7 cell line model was suitable for analyzing the relationship between one-carbon metabolism and tumor progression." (PMID 37596270, 2023). "Besides, CCK8, EdU staining, colony formation, wound healing, transwell invasion, apoptosis, cell cycle assays and nude mice tumor bearing experiments were employed to assess the role of ALDH1L1 in OSCC." (PMID 36336972, 2023). "Furthermore, downregulation of ALDH1L1 in OSCC is conducive to limit the occurrence of NADP+‐dependent reactions to meet the needs of rapid development of tumor." (PMID 36336972, 2023).
tumor (continued). "However, despite this limitation, in our study, this model provides further insight into the role of the ALDH1L1 protein as a regulator of cellular proliferation and a putative tumor suppressor." (PMID 34203215, 2021). "The elevation of this set of inflammation markers in the Aldh1l1 KO could be a common tumor-promoting response in the DEN model since a similar effect was seen with a high-fat diet, which also promotes DEN-induced tumors." (PMID 34203215, 2021). "We conclude that the ALDH1L1 loss promotes liver tumor growth without affecting tumor initiation or multiplicity." (PMID 34203215, 2021). "Some tumor type-specific DEs were observed for ALDH1L1, ALDH3B1, ALDH3B2, ALDH4A1 and ALDH7A1." (PMID 29426835, 2018). "Based on these findings, ALDH1L1 is considered as a putative tumor suppressor." (PMID 29979702, 2018). "Additionally, several studies have identified ALDH1L1 as a potential tumor suppressor." (PMID 39273288, 2024). "However, the expression profile and function of ALDH1L1 are tumor‐specific." (PMID 36336972, 2023). "ALDH1L1 expression is usually reduced or diminished in HCC, and previous studies suggested that ALDH1L1 is a tumor suppressor gene." (PMID 37596270, 2023). "These in vitro and in vivo results suggested that the downregulation of ALDH1L1 in OSCC is conducive to the demand for rapid growth of tumor cells, and the upregulation of ALDH1L1 as a target can significantly inhibit tumor development." (PMID 36336972, 2023). "We observed no reduction of tumor growth in Aldh1l1−/−; KrasLA2 mice, but treatment of these mice with phenformin decreased tumor growth by ~70%, consistent with the 70% reduction in NADH level when ALDH1L1-knockdown NSCLC cells are treated with phenformin." (PMID 32481524, 2020). "Hence, we investigated whether KRAS induces ALDH1L1 to promote tumor growth." (PMID 32481524, 2020). "Among the 4 genes, ALDH1L1 and HOPX exhibited decreased inter-tumor variance of methylation levels after NAC treatment; meanwhile, WNT5A and SOX9 showed increased inter-tumor variance." (PMID 30774927, 2019). "Our study indicates that Aldh1l1 knockout promoted liver tumor growth without affecting tumor initiation or multiplicity." (PMID 34203215, 2021). "Likewise, the following marker genes were selected for analysis in PF tumours: LAMA2, ALDH1L1, SLC6A13, IGSF1, and CXorf67 for PFA; and NELL2, DNAH1, CEP83, C9orf72, and NXNL2 for PFB tumours." (PMID 34314101, 2021). "We present evidence that, in the absence of this enzyme, liver tumors proliferate faster and grow to a larger size, whereas no apparent effect of ALDH1L1 on tumor initiation was found." (PMID 34203215, 2021). "In vivo and in vitro experiments, downregulation of ALDH1L1 in OSCC significantly inhibited the occurrence of NADP+‐dependent catalytic reactions and facilitated tumor cell growth, migration, invasion, survival, cell cycle progression, and xenograft tumor growth." (PMID 36336972, 2023).
infection (3 papers, 2019 to 2023). The state of being infected such as from the introduction of a foreign agent such as serum, vaccine, antigenic substance or organism. "Since S100 is not restricted to the astrocytic lineage but also expressed in oligodendrocytes and glial precursor cells, double labeling was performed to analyse S100 protein product in ALDH1L1+ astrocytes during infection." (PMID 31406213, 2019). "Lentiviral infection was used to overexpress ALDH1L1 in SCC‐4 and SCC‐25 cells." (PMID 36336972, 2023). "At 3 days post infection (dpi), the vast majority of the transduced cells (GFP+) were positive for the astrocytic marker Aldh1l1 and negative for the neuronal markers NeuN and DCX." (PMID 33827819, 2021).
neurodegenerative disease (2 papers, 2015 to 2025). A disorder of the central nervous system characterized by gradual and progressive loss of neural tissue and neurologic function. "Gain and loss of function experiments using the Aldh1l1‐Cre/ERT2 recombinase in models of neuroinflammatory, ischemic, and neurodegenerative diseases must account for potential mutational contributions in both astrocytes and peripheral immune cells to reported phenotypes." (PMID 39910805, 2025). "Additionally, this study showed that Aldh1l1-EGFP transgene can be a useful marker in understanding asymptomatic developing phases of mGFAP:CKO neurodegenerative disease model and potentially in understanding the roles of developmental astrocytes in other neurodegenerative diseases." (PMID 25962146, 2015).
neurological diseases (1 paper, 2022). "Next, we contrast Camk2a-neuron and Aldh1l1-astrocyte proteomes and identify brain region-specific proteomic differences within both cell types, some of which might potentially underlie the selective vulnerability to neurological diseases." (PMID 35614064, 2022).
ALDH1L1 also shares sentences with these, for which no sentence is quoted: neuroblastoma (3 papers); autism (2); Obesity (2); pilocytic astrocytoma (2); renal cell carcinoma (2); autoimmune disease (1); B-cell chronic lymphocytic leukemia (1); Cerebral ischemia (1); diabetes (1); Ewing sarcoma (1); gastric intestinal type adenocarcinoma (1); glioblastoma (1); hematological cancers (1); inflammation (1); invasive carcinoma (1); invasive ductal carcinoma (1); invasive mammary carcinoma (1); mantle cell lymphoma (1); metabolic disorders (1); periodontal disease (1); renal carcinoma (1); schizophrenia (1); squamous cell carcinoma (1).